IL23R (interleukin 23 receptor)
Diseases named in the same sentence as IL23R in open-access papers (continued):
Sharing a sentence is not in itself a finding about the gene and the disease.
Autoimmunity (20 papers, 2010 to 2024). The occurrence of an immune reaction against the organism's own cells or tissues. "We have identified an immunity-related gene, IL23R, reported in a previous microbiome genetic association study and discovered 3 other novel genes, 2 of which are involved in immune functions or autoimmune disorders." (PMID 37081571, 2023). "Among these genes, IL23R is of considerable interest: it encodes one part of the receptor for interleukin-23 (IL-23), a pro-inflammatory cytokine closely involved in autoimmunity." (PMID 37081571, 2023). "We further investigated the molecular and cellular mechanism for how IL-23R-dependent Th17 response promotes autoimmunity in Act1-deficient mice." (PMID 30013031, 2018). "Increased IL-22 and IL-23R expression during Th17 differentiation has recently been suggested as a signature for pathogenic Th17 cells that can induce autoimmunity in animal models." (PMID 24349309, 2013). "STAT4 and IL23R loci represent common susceptibility genetic factors in autoimmunity." (PMID 24312163, 2013). "STAT4 and IL23R are strongly involved in the control of the immune system through of the development and perpetuation of Th17 immune responses, which display a dominant role in autoimmunity-associated inflammation." (PMID 24312163, 2013). "The loci that were associated with the largest number of ADs include IL23R, TNFAIP3, and IL2RA, supporting an important role for T cell and innate immune response pathways in autoimmunity." (PMID 22174698, 2011). "Cells within the CD4_Stim2.Th17.1 cluster expressed genes associated with regulatory function (IL10, ITGA2), whereas cells within the CD4_Stim2.Th17.2 cluster expressed proinflammatory effectors (IFNG, IL23R, PRF1), described to be produced by pathogenic Th17 cells in autoimmunity." (PMID 35192548, 2022). "In chronic inflammatory diseases, and more specifically in autoimmunity, the CD161 fraction of memory T-cells is enriched with high IL-23R expression and is required for its inflammatory function." (PMID 32267379, 2020). "These subpopulations are phenotypically distinct: Th17 cells that mediate autoimmunity are characterized by high levels of IL-23R, IL-33 and T-bet expression when compared to their non-pathogenic counterparts that express elevated levels of IL-10." (PMID 23844143, 2013). "Usage of IL-23R reporter mice will provide us with important information on the role of IL-23 activated non-classical T cells in tissue inflammation and autoimmunity." (PMID 20356357, 2010). "Though there are no approved medications that target the interleukin-23 receptor, three interleukin-23 inhibitors or antagonists (i.e., ustekinumab, tildrakizumab, risankizumab) have been approved to treat autoimmune conditions including moderate-to-severe plaque psoriasis." (PMID 38301482, 2024).
Behçet’s disease (16 papers, 2013 to 2026). "In conclusion, this study provides evidence supporting an association between IL-12B and IL-23R gene polymorphisms and haplotypes and susceptibility to Behçet’s disease in a Turkish population." (PMID 41596568, 2026). "One year later, GWAS studies including larger cohorts were performed revealing two loci associated with Behçet's disease at GWAS level of significance: interleukin 23 receptor (IL23R) and the interleukin 10 (IL10)." (PMID 33644100, 2021). "Recent studies identified an association between Behcet’s disease (BD) and the IL-23R gene polymorphism (rs17375018) in different populations." (PMID 26222305, 2015). "Recent studies have identified a distinct subset of pediatric Behçet’s disease (BD) caused by monogenic defects with Mendelian recessive inheritance, which differs from the more common sporadic cases associated with HLA-B51, IL23R, and other polygenic variants." (PMID 41457500, 2026). "Our findings highlight the potential functional impact of specific IL-12B and IL-23R variants in the pathogenesis of Behçet’s Disease (BD)." (PMID 41596568, 2026). "On the other hand, associations of these IL23R and STAT4 polymorphisms with systemic autoimmune diseases involving uveitis, such as Behçet’s disease, Vogt-Koyanagi-Harada disease or sarcoidosis, have been described in Asian populations but not in Europeans." (PMID 24312163, 2013). "Additionally, the rs1495965 polymorphism has been reported as the stronger IL23R association with Behçet’s disease (BD), a systemic autoimmune disease involving uveitis, in a previous combined meta-analysis of two genome-wide association studies (GWASs)." (PMID 24312163, 2013). "Interestingly, genome-wide association of the interleukin (IL)23R region has been identified in many of the major forms of non-infectious uveitis, such as Behçet’s disease, ocular sarcoidosis, VKH disease, and AAU." (PMID 33912164, 2021).
multiple sclerosis (15 papers, 2009 to 2025). A progressive autoimmune disorder affecting the central nervous system resulting in demyelination. "Accordingly, the present study analyzed: (i) the potential association of these gene polymorphisms to multiple sclerosis susceptibility and (ii) the relationships of IL-27 and IL-23R SNPs with the clinical features of patients with multiple sclerosis." (PMID 35011777, 2021). "This study aimed to investigate the concentrations of IL-17 in patients with multiple sclerosis (MS) and its relationship with gender, medication, disease forms and single nucleotide polymorphisms (SNP) in IL-23R gene, including rs11209026 and rs1004819." (PMID 28717429, 2017). "Our results suggest that the use of vectors carrying sIL-23R to block the IL-23/IL-23R interaction may be a new therapeutic strategy for the treatment of multiple sclerosis." (PMID 28593439, 2017).
sarcoidosis (15 papers, 2012 to 2025). Sarcoidosis is a multisystemic disorder of unknown cause characterized by the formation of immune granulomas in involved organs. "They share the same IL23R variant (rs117633859), and they are both associated with class II HLA polymorphisms (sarcoidosis: HLA-DRB1*03, *08, *09, *11, *12, *14, and *15; VKH disease: HLA-DRB1*04) as risk factors." (PMID 32826979, 2020). "Additionally, MR analysis suggested potential causal associations of BMI, interleukin-23 receptor, and multiple circulating proteins with sarcoidosis risk, pointing to critical pathways for further exploration." (PMID 40075078, 2025). "Among those, CCDC88B and ANXA11 are potential regulators of apoptosis, whereas CCL24 was increased in broncho-alveolar lavage (BAL) of patients with stage 3 sarcoidosis compared to patients with Lo ̈ fgren syndrome and IL23R has been implicated in the formation of granulomas." (PMID 41466414, 2025). "Additionally, we find associations between sarcoidosis and genetically predicted body mass index, interleukin-23 receptor, and eight circulating proteins." (PMID 40075078, 2025). "Furthermore, our MR analysis revealed that genetically predicted higher levels of the interleukin-23 receptor were associated with a heightened risk of sarcoidosis." (PMID 40075078, 2025). "Our findings suggest that genetic control, through genetic polymorphisms in CCL24, POR, and IL23R, may have an important physiological role in the development and progression of sarcoidosis." (PMID 32826979, 2020). "The risk allele of rs117633859, a disease-associated SNP for sarcoidosis in both the Chinese and Japanese populations, and VKH disease in the Han Chinese population reduced IL23R transcription activity in HEK-293A cells and IL23 expression." (PMID 33912164, 2021). "Our analysis identifies three non-HLA susceptibility loci (CCL24, STYXL1-SRRM3, and C1orf141-IL23R) for sarcoidosis and demonstrates the importance of genetic control of CCL24, POR, and IL23R, through genetic polymorphisms, in the pathogenesis of sarcoidosis." (PMID 32826979, 2020). "DNA samples from 201 patients (111 OFG only and 90 OFG+CD) were genotyped for variants known to be strongly associated with an increased risk of CD (NOD2, IRGM, IL23R, and ATG16L1), sarcoidosis (BTNL2), and atopy (FLG)." (PMID 27306066, 2016). "We genotyped 201 patients and 1023 healthy controls for risk variants in NOD2, IRGM, IL23R, ATG16L1 (CD), BTNL2 (sarcoidosis), and FLG (atopy)." (PMID 27306066, 2016). "We therefore tested genetic variants known to be strongly associated with an increased risk of CD (NOD2, IRGM, IL23R, and ATG16L1), sarcoidosis (BTNL2), and atopy (FLG) for association with OFG." (PMID 27306066, 2016). "The most common susceptibility gene outside the MHC region is IL23R, encoding interleukin 23 receptor (IL-23R), identified from GWASs of several major non-infectious uveitis causes, such as BD, sarcoidosis, VKH, and AAU." (PMID 33912164, 2021). "We speculate that the CCL24 risk allele might be involved in a polarized Th1 response in sarcoidosis, and that POR and IL23R risk alleles may lead to diminished host defense against sarcoidosis pathogens." (PMID 32826979, 2020). "Overall, SNPs from the following genes have already been identified in previous studies on sarcoidosis (GWAS or other): CCDC88B, ANXA11, IL23R, FAM117B, CCL24, ATXN2/SH2B3." (PMID 41466414, 2025). "This suggests that impairing host defense against pathogens by downregulating the IL-23R/Th17 axis plays an important role in the development of VKH disease and sarcoidosis." (PMID 33912164, 2021).
Arthritis (14 papers, 2010 to 2026). Inflammation of a joint. "Despite having only one functional IL‐23R allele, these mice had similar susceptibility to arthritis as their WT littermates." (PMID 31778214, 2020). "In the present study, integration of genetic and clinical data revealed that IL-12B haplotypes were associated with genital ulcers and arthritis, whereas IL-23R haplotypes correlated with erythema nodosum, pathergy positivity, ocular involvement, and papulopustular lesions." (PMID 41596568, 2026). "Interestingly, while γδ T cells did not affect the disease severity, WT CD4+CCR6+ T cells were able to induce arthritis in IL‐23R deficient mice." (PMID 31778214, 2020). "Among the polymorphisms found more frequently in AS patients with arthritis, JAK2 rs7857730, IL-23R rs11209008 and rs10489630, CYP1B1 rs1056836, NELL1 rs8176786, KL rs564481, MEFV rs224204, IL-2RB rs743777, and IL-1A rs1800587 have been described." (PMID 35629038, 2022). "IL‐23 plays an important role in the development of arthritis and the IL‐23 receptor (IL‐23R) is expressed on different types of T cells." (PMID 31778214, 2020). "In conclusion, our study demonstrates that IL‐23R+ CD4+CCR6+ T cells are present in the inflamed joints during the early stages of arthritis." (PMID 31778214, 2020). "Arthritis progression and joint damage were significantly milder in IL‐23R−/− mice, which revealed less IL‐17A+ cells in their lymphoid tissues." (PMID 31778214, 2020). "Prophylactic treatment with anti-IL23R completely protected against the development of both spondylitis and arthritis, while vehicle-treated controls did develop spondylitis and arthritis." (PMID 30038617, 2018). "In contrast, treatment with anti-IL23R completely protected against the development of both spondylitis and arthritis." (PMID 30038617, 2018). "IL‐23RGFP/+ mice were used for studying the dynamics of IL‐23R+ T cells during arthritis." (PMID 31778214, 2020). "Furthermore, IL‐23R(GFP)+CD4+CCR6+ T cells are present at the site of inflammation during the early phases of arthritis." (PMID 31778214, 2020). "To assess whether IL-23 is essential for the development of spondylitis and arthritis, we prophylactically treated HLA-B27 tg rats with anti-IL23R." (PMID 30038617, 2018). "Similarly, the anti-IL23R-treated group reached an incidence of 80–100% for both spondylitis and arthritis, with similar arthritis severity between the groups." (PMID 30038617, 2018). "Several reports have demonstrated significant associations between carriage of variants in the IL-23R with psoriasis vulgaris, psoriatic arthritis, autoimmune thyroid disease, and Graves' ophthalmopathy, but not with arthritis per se, or myocardial infarct." (PMID 21253534, 2010). "Next, we assessed IL‐23R(GFP) expression in the T cells of the pLNs and the joints during the different phases of arthritis." (PMID 31778214, 2020). "This shows that memory T cell driven flare-up arthritis is IL-23-dependent, a phenomenon comparable to the prevention of EAE relapses with anti-IL-23p19 or anti-IL-23R." (PMID 23469022, 2013). "Moreover, we found that C57BL/6 (B6) mice, the most widely used inbred strain and genetic background for many transgenic and gene knockout models including IL23R-GFP reporter mice, were protected from arthritis development." (PMID 33983951, 2021). "While prophylactic blockade of the IL-23R completely prevented spondylitis and arthritis development, therapeutic blockade did not impact clinical or histological spondyloarthritis in the HLA-B27 tg rat." (PMID 34552583, 2021). "Since we detected both IL‐23R(GFP)+ γδ T cells and IL‐23R(GFP)+CD4+CCR6+ T cells in the inflamed joints of mice, we aimed to investigate which of these cells are important for the progression of IL‐23R‐dependent arthritis." (PMID 31778214, 2020). "During early arthritis, IL‐23R(GFP)+CD4+CCR6+ T cells, but not IL‐23R(GFP)+ γδ T cells, were present in the inflamed joints." (PMID 31778214, 2020).
Arthritis (continued). "To study the role of IL‐23R signaling in a T cell‐mediated inflammatory arthritis, we induced AIA in IL‐23R−/− and WT mice, and monitored joint inflammation via macroscopic scoring at days 1, 4, 7 and 10 after arthritis induction." (PMID 31778214, 2020). "Furthermore, CD4+CCR6+ T cells, but not γδ T cells, are important for IL‐23R‐dependent progression of arthritis." (PMID 31778214, 2020). "Also, in the spleen and inguinal LNs, which drain from the site of immunization, the percentage of IL‐23R(GFP) expressing CD4+CCR6+ T cells was increased during arthritis compared to naïve condition (data not shown)." (PMID 31778214, 2020). "During the early phases of arthritis, IL‐23R+CD4+CCR6+ T cells were increased in the pLNs of mice and were present in the joints, while IL‐23R+ γδ T cells were not present in the joints at this time point." (PMID 31778214, 2020). "Altogether, these data indicate that IL‐23R signaling is crucial for the progressive phase, but not for the onset of AIA and suggest that T cell infiltration in the inflamed joints plays an important role during the progression of arthritis." (PMID 31778214, 2020).
psoriatic arthritis (14 papers, 2008 to 2025). Joint inflammation associated with psoriasis. "For the IL23R SNP there was significant association in the psoriatic arthritis subtype (P trend = 0.04, OR = 0.4 95% CI 0.16 to 0.98) and a trend towards association in the enthesitis related subtype (P trend = 0.15, OR = 0.52 95% CI 0.21 to 1.28)." (PMID 21281511, 2011). "Non-MHC loci associated with psoriatic arthritis have also been identified and include IL23R (IL-23 receptor involved in the IL-17 pathway) and TRAF3IP2 (TNF-α-induced protein 3 involved in TNF-α-induced inflammation)." (PMID 41303186, 2025). "On the other hand, polymorphisms in IL23R, TNFAIP3, PTPN22 (tyrosine-protein phosphatase non-receptor type 22), IL12B, RUNX1 (CD8-lymphocyte activation and differentiation), IL13, KIR (killer-cell immunoglobulin-like receptor), and MAGI1 genes have shown association with psoriatic arthritis." (PMID 37628670, 2023).
uveitis (14 papers, 2013 to 2025). An inflammatory process affecting a part of or the entire uvea. "In uveitis studies, multiple GWAS have successfully been conducted and led to identification of novel susceptibility loci, for example, IL23R has been identified in BD, VKH and AAU." (PMID 35379982, 2022). "Genome-wide association studies (GWASs) have provided a powerful tool for the genome-wide analysis of genetic susceptibility to uveitis, revealing several genes associated with uveitis, including IL23R/C1ORF141, STAT4, and ADO/ZNF365/Egr2." (PMID 34869347, 2021). "Human genome-wide association studies (GWASs) demonstrate that several single-nucleotide polymorphisms (SNPs) in the IL-23R genes are linked to the progression of some immune disorders, including uveitis." (PMID 33816637, 2021). "Recent studies found that IL-23R gene polymorphisms are associated with uveitis in Behçet’s disease and sarcoidosis." (PMID 28558665, 2017). "Data from published studies were combined to evaluate the genetic associations between the most commonly studied polymorphisms of IL-23R, rs7517847, rs17375018, and rs11209032, and uveitis." (PMID 28558665, 2017). "In this study, we addressed the association between IL-23R polymorphisms and susceptibility to uveitis." (PMID 28558665, 2017). "The aim of this meta-analysis was to evaluate the association between the interleukin-23 receptor (IL-23R) and susceptibility to uveitis." (PMID 28558665, 2017). "This meta-analysis suggests that each allele of IL-23R, including rs7519847, rs17375018 and rs11209032 was negatively associated with uveitis." (PMID 28558665, 2017). "Six of these studies involved the association between the IL-23R gene rs7517847 polymorphism and uveitis, five studies involved rs17375018, and five studies involved rs11209032." (PMID 28558665, 2017). "Although the current study found an association between IL23R polymorphisms and AS concomitant with uveitis, some limitations need to be considered." (PMID 23840727, 2013). "In summary, our study showed that the rs17375018 of IL23R was positively associated with HLA-B27-positive AS and that the rs17375018 GG of IL23R was associated with AS concomitant with uveitis." (PMID 23840727, 2013). "In this study, the results suggested that the rs17375018 of IL23R was positively associated with HLA-B27-positive AS and that the rs17375018 GG of IL-23R was associated with AS concomitant with uveitis." (PMID 23840727, 2013). "However, our results also suggest that both rs17375018 GG and rs11209032 alleles of IL-23R are predisposing genotypes for uveitis." (PMID 28558665, 2017). "However, some studies showed significant associations between uveitis and other polymorphisms of IL-23R, such as rs924080and rs117633859." (PMID 28558665, 2017). "Some previous studies also showed an association between SNPs in IL-23R and uveitis." (PMID 28558665, 2017). "The rs7519847, rs17375018 and rs11209032 alleles of IL-23R were negatively associated with uveitis." (PMID 28558665, 2017). "Localised cytokine expression demonstrates that uveal IL-23R+ IL-17A-producing cells are both necessary and sufficient to drive uveitis in response to IL-23." (PMID 40875563, 2025). "Genes associated with the risk of developing uveitis include ERAP1, intergenic region 2p15, IL23R, IL10-IL19, IL18R1-IL1R1, IL6R, KIF21B, and EYS." (PMID 35629038, 2022). "Genotype and minor allele frequencies of IL23R and STAT4 genetic variants in uveitis patients and healthy controls." (PMID 24312163, 2013). "This study identified two new susceptibility loci associated with VKH disease reached genome-wide significance, IL23R-C1orf141 (rs117633859) and ADO-ZNF365-EGR2 (rs442309), it being of particular interest that these associations are shared by uveitis associated with both BD and AAU." (PMID 35379982, 2022). "Frequencies of alleles and genotypes of IL23R polymorphism in AS patients with uveitis, without uveitis, and controls." (PMID 23840727, 2013).
uveitis (continued). "Outside of the MHC, the fact that disease susceptibility of IL23R has been reported for several non-infectious uveitis conditions at a genome-wide significant level, suggests that the IL-23/TH17 pathway may be a common basis for the pathogenesis of non-infectious uveitis." (PMID 33912164, 2021).